OGT (O-linked N-acetylglucosamine (GlcNAc) transferase)
Diseases named in the same sentence as OGT in open-access papers (continued):
Sharing a sentence is not in itself a finding about the gene and the disease.
cancer (continued). "Although the role of Myc O-GlcNAcylation in pluripotency is not understood yet, Myc was found to be modified by OGT at Threonine 58 leading to its increased transforming activity and tumorigenicity in cancer cells." (PMID 33154167, 2021). "OGlcNAcylation, as a post-translational modification sustained by a metabolic adduct (UDP-GlcNAc), is an abundant feature of cancer cells and is, unlike other post-translational modifications, catalysed by a single enzyme, OGlcNAc transferase (OGT)." (PMID 34660272, 2021). "In summary, based on substrates of OGT, as well as their downstream effectors, which have key roles in regulating hypoxia, gene transcription, EMT, and metastasis, O-GlcNAcylation significantly modulates cancer progression." (PMID 33194731, 2020). "Thus, our findings reveal a new molecular mechanism regulating OGT and XIAP as key factors in cancer growth and invasion." (PMID 32994395, 2020). "Moreover, specific inhibitors of OGT and OGA are currently under development, offering promising future options for engaging metabolic regulation of cancer cell during cancer therapy." (PMID 31466420, 2019). "In addition, and remarkably, OGT inhibition induced the appearance of a double positive CD44+/CD133+ cell subpopulation in both primary SW480 and metastatic SW620 cancer cell lines." (PMID 31139149, 2019). "To this end, we analyzed the typical cancer stem cell traits such as clonogenic and spheroid formation abilities in the double positive CD44/CD133 cell subpopulations compared with the single positive subpopulations obtained as result of OGT inhibition." (PMID 31139149, 2019). "An immunohistochemistry (IHC) analysis of lung squamous cell carcinoma tissues showed elevated O-GlcNAcylation and OGT expression in cancer tissues compared with adjacent non-cancerous tissues." (PMID 30123425, 2018). "On the other hand, while OGT inhibitors potentially represent an interesting therapeutic strategy for cancer, they still lack specificity, are not cell permeant or are toxic." (PMID 30697194, 2018). "Additionally, a recent study has highlighted a link between OGT and the glycosidase MAN1A1 (Mannosidase alpha class 1A) in cancer cells." (PMID 30400201, 2018). "Together, these data show that OGT is crucial for the biological properties of cancer and non-cancer cell lines." (PMID 27252680, 2016). "There are no OGT inhibitors currently being tested in the clinic for cancer patients, indicating that future research is needed to develop effective OGT inhibitors." (PMID 27716624, 2016). "The clinical importance of alternations in O-GlcNAc signaling and aberrant expressions of OGT and OGA in cancer is, unfortunately, largely unknown." (PMID 25315705, 2015). "Mean expression of OGT and OGA proteins in cancer tissue were higher than in normal samples." (PMID 25315705, 2015). "Collectively, these data suggest that OGT by modification of c-Myc and PP2A could potentially regulate c-Myc stability and affect its function in cancer cell metabolism." (PMID 25250015, 2014). "Importantly, OGT and OGA are both correlated with survival and cancer recurrence in patients with CRC." (PMID 25000257, 2014). "Therefore, besides increased flux through the HBP, the altered expression of OGT and OGA also contributes to enhancement of O-GlcNAcylation in most cancers." (PMID 25426101, 2014). "Direct O-GlcNAcylation status of these proteins has not been studied but in cancer cells with increased OGT activity, HK activity was increased while PGK and PK activities were decreased." (PMID 25250015, 2014). "Using immunohistochemistry, the authors observed increased O-GlcNAcylation level and OGT expression in cancer tissues, whereas OGA expression level was not modified." (PMID 23964270, 2013). "Noteworthy, in a cancer cell line collection (60 diverse human cancer cell lines representing multiple tumor types), resistance to treatment with the PI3K inhibitor GDC-0941 correlated with OGT expression level." (PMID 23964270, 2013).
cancer (continued). "In our study, the length, age, gender and T stage of cancer did not affect the levels of OGT and O-GlcNAcation (P > 0.05)." (PMID 23554759, 2012). "Similar results were obtained when OGT was knocked down with OGT-targeted siRNA and when the co-immunoprecipitation experiments were performed in MCF7 or A549 cells, demonstrating that cellular O-GlcNAcylation status influences interactions between DBHS proteins in various types of cancer cells." (PMID 40360465, 2025). "In addition to small molecule inhibitors of OGT and OGA, several natural and synthetic compounds could reduce the proliferation of cancer cells by regulating O-GlcNAcylation modification." (PMID 41059334, 2025). "In summary, our findings demonstrate that OGT-mediated DNA damage and activate cGAS-STING pathway as an important tumor cell-intrinsic mechanism to repress antitumor immunity and provides a window for potential therapeutic opportunities for in OGT-dependent cancer." (PMID 38168435, 2024). "Exosomes derived from esophageal carcinoma cancer stem cells containing OGT target cytotoxic CD8+ cells, elevating the expression of PD-1, the receptor for PD-L1, which leads to suppression of immune activity, thus protecting cancer cells from the cytotoxic activity of the immune system." (PMID 37838167, 2023). "A lack of OGT in macrophages reduces cancer spread and chemoresistance." (PMID 38116061, 2023). "OGT and OGA also interact with epigenetic regulators, histones, and histone-remodeling complexes and could thereby alter the expression of genes involved in tumorigenesis and cancer progression." (PMID 37107691, 2023). "The enzyme O-GlcNAc transferase (OGT), which is responsible for adding GlcNAc moiety from UDP-GlcNAc on serine/threonine residues of target nuclear/cytoplasmic proteins is a key metabolic sensor, linking alteration in nutrient status and signaling pathways in cancer." (PMID 37152043, 2023). "Targeting OGT may have clinical utility, as seen with other inhibitors that target broad sets of proteins, including HDAC or proteasome inhibitors that are currently used in the clinic to treat cancer." (PMID 37838167, 2023). "Below, we highlight a few representative examples, in which the OGT/OGA–protein interactions have been validated by orthogonal methods, such as immunoprecipitation, to demonstrate the diverse molecular impacts of these PPIs on the malignant programming of cancer cells." (PMID 36291918, 2022). "The results showed that OGT and OGA expression levels changed in almost all cancers to varying degrees, suggesting that O-GlcNAcylation level and the levels of O-GlcNAc circulating enzymes might have significance for early cancer screening and prognosis." (PMID 36104770, 2022). "It has been shown in both non-tumor (293A-TOA) and cancer (HCT116) cells that TMG treatment induces intron retention in the OGT transcript to regulate OGT expression; the intron retention is responsive to changes in O-GlcNAc levels and is regulated by a conserved intronic splicing silencer." (PMID 33801653, 2021). "Moreover, UNC5C and UNC5D transcripts remained undetectable upon OGT silencing (Decourcelle, A.; Dehennaut, V.; Université de Lille, CNRS, Inserm, CHU Lille, UMR9020-U1277—CANTHER—Cancer Heterogeneity, Plasticity and Resistance to Therapies, F-59000 Lille, France." (PMID 33126652, 2020). "However, the mechanisms that regulate OGT expression in other types of cancer cells are still not well understood." (PMID 32994395, 2020). "Since many of these cancers also had increased OGT RNA and protein levels, it is not clear whether elevated O-GlcNAcylation is due to increased UDP-GlcNAc substrate availability, increased OGT levels, or both." (PMID 31272438, 2019).
cancer (continued). "However, this was not the case in our cancer cell system, because the expression levels of OGT and OGA were unaffected by GFAT1 silencing." (PMID 31645543, 2019). "Thus, the nutrient-sensing dynamics of OGT and the HBP may negatively affect normal metabolic states, which ultimately leads to cancer." (PMID 27716624, 2016). "Importantly, levels of O-GlcNAc, OGT, and OGA have correlated with aggressiveness (e.g., Gleason score for prostate cancer) in a number of patient tumor samples including prostate, breast, endometrial, and bladder cancers." (PMID 27148477, 2016). "However, our findings resemble the findings in other cancers, particularly with regard to the OGT enzyme, regardless of tumor type." (PMID 25315705, 2015). "However, it remains unclear how O-GlcNAcylation and O-GlcNAc cycling enzymes, O-GlcNAc transferase (OGT) and O-GlcNAcase (OGA), affect the development of cancer in animal models." (PMID 25000257, 2014). "Interestingly, no mutations in OGT and OGA genes have been reported in human cancers, suggesting that these enzymes are tightly conserved." (PMID 25426101, 2014). "However, the mechanism by which OGT and O-GlcNAc regulate CSCs in cancer is not clear." (PMID 40136647, 2025). "Thus, in cancer cells, OGT is likely to exert its full activity without being restricted by substrate limitation, which would positively correlate the OGT protein level with the O-GlcNAcylation activity, the NRF1 protein level, and the expression levels of proteasome subunit genes." (PMID 29941490, 2018). "Importantly, a recent study has revealed that activated ERK 1/2 signaling leads to increased expression of OGT and O-GlcNAcylation levels in various cancers, indicating that there is possibly positive feedback between the ERK 1/2 signaling pathway and the O-GlcNAcylation level in cancer cells." (PMID 27542217, 2016). "There is no clear evidence that OGT can be targeted for O-GlcNAcylation of RNA Pol II, resulting in transcriptional activation of CSC marker genes in SETD5-overexpressed cancer cells." (PMID 37963940, 2023). "In conclusion, the expression patterns of OGT and OGA are diverse and have both positive and negative effects on clinicopathological features, which indicates that the role of O-GlcNAc in cancer is very complex." (PMID 36104770, 2022). "AUC values for eight cancers (e.g., ACC) were up to at least 0.9, suggesting conspicuous effects of OGT expression in distinguishing cancers from noncancers." (PMID 35356257, 2022). "AMPK is O-GlcNAc modified in vitro by OGT at its α and ɣ subunits, leading to increased AMPK activity; however, the role of this O-GlcNAcylation has not been examined in the cancer context." (PMID 31272438, 2019). "Given that cellular UDP-GlcNAc was significantly higher in these cancer cells than MECs, it is plausible that the levels of protein O-GlcNAcylation is predominantly controlled by HBP flux rather than OGT expression in these cells." (PMID 31645543, 2019). "The expressions of OGT and EZH2 proteins in three cancer breast cell lines (MCF7, T47D and MDA-MB-231) and one non-neoplastic breast cell line (MCF10A) were compared." (PMID 29864144, 2018). "The results of chromatin immunoprecipitation experiments showed that both EZH2 and OGT are targeted to the promoter regions of FOXA1 and FOXC1 and knockdown of EZH2 or OGT affects expression of studied genes in breast non-malignant (MCF10A) and cancer cells (MCF7, T47D and MDA-MB-231)." (PMID 29864144, 2018).
tumor (139 papers, 2012 to 2026). "In clinical NB cases, higher OGT, FOXC1, ASNS, GPT2, CBS, or FTH1 levels are correlated with worse survival, while lower ecircOGT or OGT-570aa expression is associated with tumor progression." (PMID 40416363, 2025). "OGT and O-GlcNAcylation are overexpressed in many tumors and closely associated with tumor growth, invasion, metabolism, drug resistance, and immune evasion." (PMID 39285476, 2024). "For instance, increased glucose uptake in M2-like tumor-associated macrophages fuels HBP for lysosomal OGT-mediated Cathepsin B O-GlcNAcylation to elevate its mature form and then promotes tumor metastasis and chemoresistance." (PMID 38575607, 2024). "OGT has been implicated in promoting tumor immune evasion by inhibiting the lysosomal degradation of PD-L1." (PMID 39285476, 2024). "To further probe the effect of OGT deficiency on tumor growth, we subcutaneously injected control or OGT-depleted HT-29 cells into nude mice." (PMID 38778217, 2024). "OGT has been implicated in enhancing tumor formation and tumorigenesis associated with HPV infection." (PMID 38827513, 2024). "Enhanced levels of O‐GlcNAcylation in tumor cells have been linked to cell death in pharmacological investigations of OGT or OGA inhibition." (PMID 38116061, 2023). "In esophageal carcinoma, the expression of OGT is elevated and is associated with the immunosuppression activity of the tumor." (PMID 37838167, 2023). "While this association suggests OGT is a tumor promoter and novel therapeutic target, there is also evidence in AML and MDS that O-GlcNAcylation helps slow disease progression." (PMID 34868034, 2021). "Overexpression of OGT in tumor tissues and the association between high O-GlcNAcylation and poor patients’ outcome have been previously reported in CCA." (PMID 29915392, 2018). "Univariate analysis showed that age, tumor necrosis, and OGT expression were associated with reduced OS in cohort A patients." (PMID 30123425, 2018). "OGT is an enzyme that adds O-linked β-N-acetylglucosamine (O-GlcNAc) moieties to various nuclear and cytosolic proteins and gained interest as anti-tumor therapeutic target in recent years." (PMID 25149532, 2014). "The authors pointed out that tumors that eventually grew from OGT knockdown cells restored OGT expression, suggesting a selective pressure against tumor cells that are deficient in OGT." (PMID 24918087, 2014). "Amongst the most differentially expressed genes we identified between GDC-0941-sensitive and GDC-0941–resistant tumor cell lines is O-linked β-N-acetylglucosamine transferase (OGT)." (PMID 23029544, 2012). "Importantly, recent studies have implicated the role of elevated OGT and O-GlcNAc in regulating CSCs phenotypes and tumor initiation." (PMID 40136647, 2025). "Additionally, O-GlcNAcylation catalyzed by OGT, is overexpressed in ccRCC and linked to tumor growth, invasion, metabolism, therapy resistance, and immune evasion." (PMID 40852041, 2025). "Based on these studies, OGT-mediated O-GlcNAcylation is associated with tumor treatment resistance." (PMID 39285476, 2024). "In addition, in vivo xenograft experiments showed that depletion of OGT reduced the tumor weight and volume caused by RALY overexpression." (PMID 38993567, 2024). "Interestingly, many previous studies have shown that elevated OGT is associated with tumor progression." (PMID 36104770, 2022). "In view of the binding affinity of miR-181d to OGT confirmed by dual luciferase reporter assay, it would be reasonable to speculate that the tumor-supporting properties of miR-181d are associated with OGT inhibition." (PMID 34876558, 2021). "Most importantly, we found that reducing OGT in HeLa cells caused decreased tumor growth in vivo." (PMID 27331873, 2016). "Reducing OGT in HeLa cells caused decreased tumor growth in vivo." (PMID 27331873, 2016).
tumor (continued). "The presence of increased levels of OGT transcript in tumor tissue was more frequently associated with greater total TFG score (≥14 points) as well as deeper and more aggressive tumor growth with submucosa or cartilage infiltration and disseminated type of invasion." (PMID 25315705, 2015). "Moreover, the authors noted that the reduction in OGT expression in tumor cells was associated with decreased expression of MMP-2, MMP-9 and VEGF and blocked bone metastasis." (PMID 25315705, 2015). "The authors suggested that increased O-GlcNAc modification by OGT silencing or OGA inhibition in tumor cells may be associated with decreased E-cadherin expression and may also be linked with higher incidence of metastases in the study model." (PMID 25315705, 2015). "Moreover, in murine xenograft GB, miR-7 was capable of inhibiting tumor angiogenesis and growth by directly targeting the O-linked N-acetylglucosamine (GlcNAc) transferase (OGT) gene, and these same phenotypes were achieved when miR-7 targeted Raf-1 proto-oncogene (RAF1) in GB cell lines." (PMID 38473710, 2024). "Combining small‐molecule inhibitors of O‐GlcNAc cycling enzymes (OGT/OGA) with autophagy modulators offers a novel strategy to overcome tumor drug resistance." (PMID 41540817, 2026). "In mouse xenografts, treatment with the O-GlcNAc transferase (OGT) inhibitor OSMI-1 attenuated the accelerated tumor growth driven by miR-27a-5p inhibition, supporting an O-GlcNAcylation-dependent mechanism in vivo." (PMID 41772703, 2026). "Given its central role in tumour signalling and metabolic remodelling, developing specific inhibitors (e.g., the OGT inhibitor OSMI‐1) or combination therapies targeting this modification holds significant clinical potential." (PMID 41540817, 2026). "In hepatocellular carcinoma models, USP8 inhibition suppresses tumor growth and metastasis by inducing ferroptosis through OGT destabilization to disrupt OGT-SLC7A11 axis; USP8 promotes cancer progression by stabilizing β-catenin and inhibiting ferroptosis." (PMID 40813720, 2025). "OGT function and O‐GlcNAcylation regulation are involved in tumor formation, survival, metastasis, and angiogenesis." (PMID 40237201, 2025). "Among them, MZF1, OGT, LHX4, and MED12 have been implicated in tumor stemness, drug resistance, and immune escape mechanisms." (PMID 40963600, 2025). "For instance, OGT overexpression modifies p120 and β‐catenin, leading to reduced E‐cadherin on the cell surface, weakened intercellular adhesion, and facilitated tumor cell detachment and distant dissemination." (PMID 41394960, 2025). "In pancreatic ductal adenocarcinoma, OGT promotes tumor recurrence by modifying and stabilizing the transcription factor SOX2, while OSMI treatment markedly reduces the O‐GlcNAcylation level and stability of SOX2, thus decreasing recurrence." (PMID 41394960, 2025). "Recent studies have shown that OGT and O-GlcNAc play a critical role in maintaining and driving tumor initiation and CSCs phenotypes." (PMID 40136647, 2025). "Studies have shown that OGT is directly or indirectly involved in the regulation of tumor metabolic processes." (PMID 39285476, 2024). "A significant positive correlation tendency between OGT mRNA expression and individual different tumor stages was observed." (PMID 38168435, 2024). "In most human tumors, OGT functions as an oncoprotein, promoting tumor growth, metastasis, and drug resistance by activating signaling pathways such as proliferation, EMT, and anti-apoptosis." (PMID 39285476, 2024). "Overexpressed OGT substantially promoted tumor growth in vivo, with elevated PRPS1 O-GlcNAcylation and activity." (PMID 37308732, 2024). "To corroborate with these findings, we analyzed OGT mRNA expression in tumor tissues and the matching normal tissues based on The Cancer Genome Atlas (TCGA) gene expression datasets." (PMID 38778217, 2024).